SIRT1 (sirtuin 1)
Diseases named in the same sentence as SIRT1 in open-access papers (continued):
Sharing a sentence is not in itself a finding about the gene and the disease.
melanoma (continued). "Our data suggest the involvement of BUB family proteins in the anti-proliferative response of SIRT1 inhibition in melanoma cells." (PMID 24743044, 2014). "Mechanistically, USP22 controls melanoma metastasis by targeting SIRT1/PTEN/PI3K signaling axis." (PMID 39135915, 2024). "Notably, SIRT1 expression is positively correlated with the EMT marker vimentin using Xiangya melanoma datasets and TCGA datasets." (PMID 39135915, 2024). "We took a further step to elucidate the role of USP22/SIRT1 interaction in melanoma metastasis." (PMID 39135915, 2024). "It has been reported that SIRT1 contributes to melanoma progression." (PMID 39135915, 2024). "Mechanistically, USP22 controls melanoma metastasis through the SIRT1/PTEN/PI3K pathway." (PMID 39135915, 2024). "SIRT1 is a target of miR-34a, as it has been demonstrated in a mouse melanoma cell line." (PMID 35163570, 2022). "Interestingly, the NAD+-dependent deacetylase enzyme SIRT1 is required for lamellipodia extension and migration of melanoma cells." (PMID 32153556, 2020). "It was shown that SIRT1 is overexpressed in human melanoma tissues and cell lines." (PMID 33178616, 2020). "Interestingly, in ~65% of the melanoma tissues we tested, SIRT1 was unexpectedly found in the cytoplasm instead of the nucleus." (PMID 33178616, 2020). "The fact that E-cadherin may be downregulated through the activation of autophagy has been already demonstrated on melanoma and hepatoma cells in which SIRT1 and SPHK1, respectively, regulate this process." (PMID 32714931, 2020). "Furthermore, SIRT1&2 knockdown inhibits proliferation and decreases colony formation in melanoma cells." (PMID 33028392, 2020). "SIRT1 is also essential for lamellipodium extension and the migration of melanoma cells." (PMID 29374154, 2018). "We first examined the effect of SIRT1 on Beclin 1 acetylation in melanoma cells." (PMID 29374154, 2018). "We speculated that autophagy might participate in the lysosomal degradation of E-cadherin, and we investigated the role of SIRT1 in regulating autophagy in melanoma cells." (PMID 29374154, 2018). "We further investigated whether SIRT1 promotes the metastatic potential of melanoma cells by regulating the EMT." (PMID 29374154, 2018). "Therefore, our study demonstrates a novel mechanism for SIRT1 in promoting EMT in melanoma cells and provides a potential therapeutic target for metastatic melanoma." (PMID 29374154, 2018). "Moreover, SIRT1 knockdown significantly weakened melanoma cell migration and invasion compared with the control." (PMID 29374154, 2018). "We next investigated the exact mechanism of SIRT1-mediated E-cadherin reduction in melanoma cells." (PMID 29374154, 2018). "Overall, our findings reveal a novel molecular mechanism for SIRT1 in melanoma metastasis, indicating that SIRT1 may serve as a viable therapeutic target for metastatic melanoma." (PMID 29374154, 2018). "Particularly, we observed a SIRT1 up-regulation in our melanoma progression model." (PMID 29383100, 2017). "Sirt1 stable silencing increased Mxd1 mRNA expression and led to down-regulation of MYC targets, such as Cdkn1a, Bcl2 and Psen2, whose upregulation is associated with human melanoma aggressiveness and poor prognosis." (PMID 29383100, 2017). "Depending on the ROS-induced DNA damage, the SIRT1 relocation at Mxd1 sequence and stress-induced SIRT1 recruited repressive protein complexes might vary along the different steps of melanoma progression." (PMID 29383100, 2017). "SIRT1 is well known to be responsive to stress and participates in the establishment and development of several tumors, including prostate, lung, breast, ovarian, hepatocellular carcinomas, and melanoma." (PMID 29383100, 2017).
melanoma (continued). "Furthermore, SIRT1 level and activity are dramatically inhibited in BRAFV600E-mutated melanoma cells sensitive to PLX4032, whereas they remain elevated in their resistant counterpart." (PMID 24742694, 2014). "Noteworthy, SIRT1 level decreases in PLX4032-treated melanoma cells after 96 hours." (PMID 24742694, 2014). "However, the modulation of SIRT1 and its association with UBC needs to be explored in melanoma and other cancers." (PMID 24743044, 2014). "Here, we demonstrate that SIRT1 is a critical regulator of melanoma cell proliferation." (PMID 24742694, 2014). "Interestingly, SIRT1 level and activity are enhanced in the PLX4032-resistant BRAFV600E-mutated melanoma cells compared with their sensitive counterpart." (PMID 24742694, 2014). "Whereas AMPK has been recently implicated in melanoma disease, the role of SIRT1 has never been investigated." (PMID 24742694, 2014). "This study was designed to investigate the role of SIRT1 in melanoma cells." (PMID 24742694, 2014). "Likewise, immunofluorescences showed that SIRT1 mainly localized to the nucleus in melanoma cells and that SIRT1 reduction paralleled that of MITF." (PMID 24742694, 2014). "However, these SIRT1 inhibitors are known to inhibit other sirtuins, as well, albeit at higher concentrations, suggesting the potential of concomitantly inhibiting multiple sirtuins for effective melanoma management." (PMID 33178616, 2020). "However, the molecular mechanism of SIRT1 in melanoma metastasis remains to be clarified." (PMID 29374154, 2018). "In our study, we hypothesized that SIRT1 promotes melanoma metastasis by inducing the EMT." (PMID 29374154, 2018). "However, the precise regulatory mechanisms and signaling pathways underlying the SIRT1-mediated EMT and melanoma metastasis remain unclear." (PMID 29374154, 2018). "Moreover, SIRT1 overexpression relieves the senescence-like phenotype and the proliferation arrest caused by MITF knock-down, thereby demonstrating that SIRT1 is an effector of MITF-induced proliferation in melanoma cells." (PMID 24742694, 2014). "Likewise, SIRT1 suppression induced senescence-like phenotypes in different melanoma cells lines." (PMID 24742694, 2014). "Whether SIRT1 plays a role in melanoma biology remained poorly elucidated." (PMID 24742694, 2014). "One of its primary mechanisms of action involves the activation of the Sirtuin 1 (SIRT1) pathway, which suppresses melanoma cell growth by inducing cell cycle arrest and promoting mitochondrial-mediated apoptosis." (PMID 40507159, 2025). "Ubiquitin‐specific protease 22 (USP22) stabilizes SIRT1 and activates the PI3K/Akt/mTOR pathway through enhancing SIRT1‐mediated PTEN deacetylation, thereby promoting melanoma metastasis both in vitro and in vivo." (PMID 39135915, 2024). "Tenovin-1 and -6 inhibit SIRT-1 and SIRT-2 and decrease cell growth in Burkitt’s lymphoma and melanoma cells, gastric cancer cells, and NSCLC." (PMID 36080416, 2022). "Histone deacetylase SIRT1 is downregulated by ONC, and it was reported to induce EMT and facilitate melanoma metastasis." (PMID 35163570, 2022). "Earlier, we have demonstrated that chemical inhibition of SIRT3 along with SIRT1 decreased aerobic glycolysis (glucose uptake, lactate production and NAD+/NADH ratio) in melanoma cells." (PMID 33937086, 2021). "Another epigenetic player investigated for its involvement in CM initiation is SIRT1 (class III HDAC proteins), which was found overexpressed in human melanoma cells and tissues in comparison to normal skin and melanocytes." (PMID 34575678, 2021). "In this article, we have presented a case for the combined inhibition of SIRT1 and SIRT3 for melanoma management." (PMID 33178616, 2020).
melanoma (continued). "In a recent study, we have shown that dual inhibitor of SIRT1 and SIRT3 by 4′-bromo-resveratrol had significant anti-proliferative effects against melanoma cells." (PMID 33178616, 2020). "Recent studies from our laboratory together with other publications suggest the pro-proliferative roles of SIRT1 and SIRT3 in melanoma." (PMID 33178616, 2020). "Overall, these studies suggest that both SIRT1 and SIRT3 regulate cellular metabolic homeostasis, further emphasizing the importance of targeting these two sirtuins in melanoma." (PMID 33178616, 2020). "Augmented endocytosis of E-cadherin has also been reported and autophagy-induced degradation, due to overexpression of SIRT1, SPHK1, or PHF8 have been described in melanoma and hepatocarcinoma." (PMID 32714931, 2020). "Based on available data from our laboratory and elsewhere, both SIRT1 and SIRT3 appear to play important roles in melanoma progression." (PMID 33178616, 2020). "Most studies of sirtuin functions in melanoma have concentrated on SIRT1; however, our group and others have also demonstrated the possible involvement of SIRT2 in the multidrug resistance of melanomas." (PMID 31091806, 2019). "In the present study, we found that SIRT1 promoted the EMT through deacetylation of Beclin 1 and autophagic degradation of E-cadherin in melanoma cells." (PMID 29374154, 2018). "Our findings define a novel molecular mechanism by which SIRT1 regulates the EMT and metastatic potential of melanoma cells." (PMID 29374154, 2018). "Here we report that SIRT1 induces the epithelial–mesenchymal transition (EMT) by accelerating E-cadherin degradation via autophagy and facilitates melanoma metastasis." (PMID 29374154, 2018). "In conclusion, the present study provides conclusive evidence that SIRT1 promotes the EMT by deacetylating Beclin 1 and then accelerates the autophagic degradation of the epithelial marker E-cadherin in melanoma cells." (PMID 29374154, 2018). "SIRT1 promoted Mxd1 silencing, which led to increased activity of MYC oncogene contributing to melanoma progression." (PMID 29383100, 2017). "Since in our model SIRT1 represses Mxd1 gene expression, we suggest that MYC is activated in melanoma progression." (PMID 29383100, 2017). "In our melanoma model, the expression of these genes is increased in the tumor cell lines and, as hypothesized, there was a significant reduction of Cdkn1a, Bcl2 and Psen2 expression in SIRT1-silenced 4C11+ melanoma cell line (respectively) compared to non-silenced cell lines." (PMID 29383100, 2017). "The qRT-PCR and immunoblot analyses showed that tenovin-1 inhibition of SIRT1 resulted in a downregulation of BUB3, BUB1 and BUBR1 in multiple melanoma cell lines." (PMID 24743044, 2014). "Our results show that SIRT1 over-expression rescued melanoma proliferation arrest mediated by MITF knock-down, thereby indicating that SIRT1 is an effector of MITF-induced cellular proliferation." (PMID 24742694, 2014). "Therefore, deregulation of SIRT1 might play an important role in melanoma pathogenesis." (PMID 24742694, 2014). "SIRT1 forced expression, led to an increased SIRT1 activity, and prevented SA-βGal staining mediated by MITF-suppression in melanoma cells." (PMID 24742694, 2014). "SIRT1 also deacetylates Beclin 1, leading to upregulated autophagy and degradation of E-cadherin accompanied by increased metastatic potential of BRAF-mutant melanoma cells." (PMID 39935431, 2025). "The dual SIRT1/SIRT3 inhibitor 4’-BR showed caspase 3-dependent apoptosis, p21-dependent cell cycle arrest, and metabolic reprogramming (decreased glucose uptake, lactate formation, and NAD+/NADH ratio) in melanoma cells." (PMID 39935431, 2025). "In melanoma cells, SIRT1 silences MXD dimerization protein 1 (Mxd1) by binding to DNMT3B, thereby increasing resistance to dead-cancer-induced stress, which leads to increased Myc activity and drives melanoma progression." (PMID 39479446, 2024).
melanoma (continued). "To determine whether USP22 activates the PI3K/Akt/mTOR pathway via SIRT1‐mediated PTEN deacetylation, we used siRNA to silence the expression of SIRT1 in USP22‐overexpressing melanoma cells." (PMID 39135915, 2024). "Sirtuin 1 (SIRT1) induces EMT and facilitates melanoma metastasis." (PMID 35163570, 2022). "George and colleagues showed that the dual inhibitor of SIRT-1 and SIRT-3, 4-Bromo resveratrol, obtained with a chemical modification from resveratrol is able to reduce cell growth and induce apoptosis in melanoma cells in vitro and in vivo through metabolic reprogramming." (PMID 36080416, 2022). "Interestingly, a recent study showed that dual inhibition of SIRT1 and SIRT3 mediated by 4′-bromo-resveratrol inhibits melanoma cell proliferation and growth." (PMID 34575678, 2021). "Similar to SIRT1 and SIRT3, SIRT6 has been shown to possess a pro-proliferative role in melanoma." (PMID 33178616, 2020). "Although the role of SIRT1 in tumorigenesis in melanoma cells has been controversial, our data showed that overexpression of SIRT1 WT, but not SIRT1 HY, led to a reduced cell proliferation and cell viability rate compared to that of the mock control." (PMID 32636443, 2020). "The demonstrated roles of SIRT1 and SIRT3 in melanoma suggest that their inhibition may be useful in melanoma management." (PMID 33178616, 2020). "Thus, our data provide ample evidence that cryptolepine-induced inhibition of mTOR signaling and SIRT1 protein levels resulted in reduction of PGC-1α protein levels and mitochondrial biogenesis in cryptolepine-treated melanoma cells." (PMID 28473727, 2017). "Surprisingly, the ChIP assay along melanoma progression stages did not confirm this interaction in pre-malignant 4C melanocytes, but SIRT1/Mxd1 interaction was remarkably evident at later stages." (PMID 29383100, 2017). "Since Mxd1 is downregulated by SIRT1 in 4C11- and 4C11+ tumor cell lines, we have postulated that MAX could become more available to MYC binding in these melanoma cells." (PMID 29383100, 2017). "Our data indicate that SIRT1 and DNMT3B co-participate in Mxd1 epigenetic silencing in melanoma." (PMID 29383100, 2017). "For instance the axis MALAT1/miR-211/SIRT1 is increased in vitiligo keratinocytes, protecting these cells from UVB-induced DNA damage and promoting their differentiation which correlate with a lower incidence of melanomas and other cancers in vitiligo patients." (PMID 35883477, 2022). "Considering the reversibility of epigenetic changes, the participation of SIRT1 and other epigenetic components in reducing Mxd1 expression and in increasing MYC oncogenic activity might have prognostic and therapeutic potential in melanoma." (PMID 29383100, 2017). "Furthermore, we found that cryptolepine targets mitochondrial dynamics and biogenesis in melanoma cells and that these effects were accompanied by activation of AMPKα1/2-LKB1, inhibition of mTOR signaling, and a reduction in the levels of c-Myc, SIRT1 and PGC-1α protein." (PMID 28473727, 2017). "1,25(OH)2D3 induction of SIRT1 levels was not restricted to CRC cells and took place in other unrelated cancer cell lines from pancreas or melanoma suggesting that this might be a general mechanism for 1,25(OH)2D3 action." (PMID 39494323, 2024).
diabetic cardiomyopathy (64 papers, 2014 to 2026). Diabetic cardiomyopathy is a disorder of the heart muscle in people with diabetes. "Some studies have shown that LF10 inhibits MAPK phosphorylation and attenuates the injury caused through diabetic cardiomyopathy by restoring SIRT1." (PMID 38543095, 2024). "Abnormal cardiac function in diabetic cardiomyopathy mice was also associated with reduced SIRT1 expression." (PMID 33430144, 2021). "To further unravel the molecular mechanisms implicated in the antioxidative effects of BAK against diabetic cardiomyopathy, we have focused on the SIRT1/Nrf2 signaling pathway." (PMID 33062139, 2020). "Continuing research into the mechanisms underlying SIRT1-based treatment is necessary to further improve the efficacy and specificity of drugs against diabetic cardiomyopathy." (PMID 31076562, 2019). "Moreover, rosmarinic acid diminished ROS generation and apoptosis caused by diabetic cardiomyopathy, while upregulating SIRT1 and PGC‐1α expressions." (PMID 39723061, 2024). "This study investigates the relationship between dapagliflozin therapy and atrial tachyarrhythmia in diabetic cardiomyopathy, with a focus on the role of SIRT1." (PMID 39636756, 2025). "Overall, SIRT1 plays a protective role in diabetic cardiomyopathy by reducing apoptosis, regulating autophagy and mitophagy, and modulating calcium channel activity." (PMID 39636756, 2025). "Together, these insights underscore the importance of further research into the role of SIRT1 in cardiac health and disease, particularly in the context of diabetic cardiomyopathy and atrial arrhythmias." (PMID 39636756, 2025). "Curcumin has been shown to enhance apoptosis in diabetic rats and help cure diabetic cardiomyopathy by modifying the SIRT1-Foxo1 and PI3K-Akt pathways." (PMID 41567643, 2025). "SGLT2i activate SIRT1 and its downstream signals, which helps to explain how SGLT2i decrease oxidative stress in diabetic cardiomyopathy." (PMID 37055837, 2023). "The antioxidant effect induced by the activation of SIRT1 in T1DM diabetic cardiomyopathy mainly includes the SIRT1/Nrf2 signalling pathway, while in T2DM, it includes the Sirt1/forkhead box class O1 (FOXO1) signalling pathway." (PMID 37055837, 2023). "Overexpressed microRNA-22 can directly bind to the 3′untranslated repeats (3′-UTRs) of its target gene Sirt1 and alleviate diabetic cardiomyopathy OS via upregulating Sirt1 in vivo and in vitro." (PMID 35103095, 2022). "Overall, these findings suggest that SIRT1-mediated autophagy participates in alleviating diabetic cardiomyopathy condition." (PMID 35909524, 2022). "Kaempferol inhibited diabetic cardiomyopathy in rats through a hypoglycemic effect and upregulation of SIRT1." (PMID 36338468, 2022). "For the PI3K/Akt signaling pathway, the gene Sirt1 participates in diabetic myocardial injury and the occurrence and development of early diabetic cardiomyopathy by negatively regulating the PI3K/Akt/MTOR signaling pathway." (PMID 36141135, 2022). "SIRT1 activation by resveratrol can alleviate myocardial injuries in diabetic cardiomyopathy via regulation of mitochondrial function mediated through SIRT1-triggered PGC1α deacetylation and Nrf2 activation." (PMID 34071497, 2021). "Existing results have suggested that SIRT1 inhibits apoptosis from hypoxic stress and diabetic cardiomyopathy." (PMID 34220528, 2021). "Simultaneously, THC has been reported to alleviate diabetic cardiomyopathy mainly by attenuating oxidative stress and fibrosis via increasing the expression of SIRT1." (PMID 34187277, 2021). "Simultaneously, THC has been reported to alleviate diabetic cardiomyopathy mainly by attenuating oxidative stress and fibrosis via activating the expression of SIRT1." (PMID 34187277, 2021). "Resveratrol stimulates autophagic flux, improving diabetic cardiomyopathy in a diabetic mouse model mediated by a decrease in p62 protein levels, facilitating SIRT1 activity." (PMID 33498216, 2021).